MYLKP1 (myosin light chain kinase pseudogene 1)
Synonyms: MYLKP
Gene: Unprocessed pseudogene on chromosome 3 (75,328,549 to 75,339,071, reverse strand). Ensembl gene ENSG00000228868.
Diseases named in the same sentence as MYLKP1 in open-access papers:
MYLKP1 is named in the same sentence as 11 diseases in open-access papers, as found by Europe PMC text mining. Sharing a sentence is not in itself a finding about the gene and the disease. The quoted sentences say what the papers report.
colon cancer (3 papers, 2018 to 2025). "In this study, we further validate MYLKP1 as an oncogene via elucidation of the functional role of MYLKP1 genetic variants in colon cancer risk." (PMID 30161129, 2018). "Genotyping studies identified two MYLKP1 SNPs (rs12490683; rs12497343) that significantly increase risk of colon cancer in African Americans compared to African American controls." (PMID 30161129, 2018). "Two known MYLKP1 SNPs, rs12497343 (C>G) and rs12490683 (G>A), affected MYLKP1 promoter activity and were significantly associated with colon cancer risk in African Americans." (PMID 30161129, 2018). "These SNPs are found to further enhance the promoter activity of MYLKP1 compared to the wild type, indicating that MYLKP1 functions as a colon cancer‐promoting pseudogene, with its genetic variants exacerbating colon cancer risk specifically in African American populations." (PMID 40556338, 2025). "The pseudogene MYLKP1, derived from MYLK which encodes myosin light chain kinase (MLCK), exhibits high expression in lung and colon cancer cell lines and tissues but is absent in normal lung or colon tissue." (PMID 40556338, 2025). "We previously reported that MYLKP1, the pseudogene of MYLK that encodes myosin light chain kinase (MLCK), is highly expressed in lung and colon cancer cell lines and tissues but not in normal lung or colon." (PMID 30161129, 2018).
lung adenocarcinoma (3 papers, 2018 to 2025). A carcinoma that arises from the lung and is characterized by the presence of malignant glandular epithelial cells. "The promoter activity of MYLKP1 is low in normal bronchial epithelial cells but significantly elevated in lung adenocarcinoma cells." (PMID 40556338, 2025). "MYLKP1, a partial duplicate of the MYLK gene encoding smMLCK, shares ~89.9% promoter homology but shows low activity in normal cells and high activity in lung adenocarcinoma cells." (PMID 40556338, 2025). "Despite strong homology with the smMLCK promoter (~90%), the MYLKP1 promoter is minimally active in normal bronchial epithelial cells but highly active as the smMLCK promoter in lung adenocarcinoma cells." (PMID 30161129, 2018). "The MYLKP1 promoter is minimally active in normal bronchial epithelial cells but highly active in lung adenocarcinoma cells." (PMID 30161129, 2018).
colorectal cancer (1 paper, 2018). A primary or metastatic malignant neoplasm that affects the colon or rectum. "P values and odds ratios for associations with MYLKP1 polymorphisms in African and European American colorectal cancer, adjusted for age, sex, and West African ancestry." (PMID 30161129, 2018). "Selected MYLKP1 promoter SNPs were genotyped in a colorectal cancer cohort and further assessed by luciferase reporter promoter activity assays." (PMID 30161129, 2018). "Only the MYLKP1 SNP s12490683 achieved statistical significance in the analysis of European American colorectal cancer cases and controls." (PMID 30161129, 2018). "Fourteen MYLKP1 SNPs (MAFs >0.01) residing within the 4 kb MYLKP1 promoter region, the core 1.4 kb of MYLKP1 gene, and a 4 kb enhancer region were selected and genotyped in a colorectal cancer cohort." (PMID 30161129, 2018).
lung carcinoma (1 paper, 2018). "Histological staining demonstrated increased MYLKP1 expression in A549 lung cancer cells corresponding with significant proliferation (p<0.05), consistent with our previous report that MYLKP1 promotes proliferation in cancer cell lines and tissues." (PMID 30161129, 2018). "Proliferation and migration assays were performed in MYLKP1-transfected colon and lung cancer cell lines (H441, A549) and commercially-available normal lung and colon cells." (PMID 30161129, 2018).
cancer (7 papers, 2012 to 2025). A tumor composed of atypical neoplastic, often pleomorphic cells that invade other tissues. "We attempted to elucidate a potentially active biological role for MYLKP1 and to clarify its participation as a candidate gene in cancer risk." (PMID 30161129, 2018). "Together, these studies, which provide further support for the functional involvement of pseudogenes in human pathobiology, suggest MYLKP1 should be considered as a novel diagnostic or therapeutic target in human cancer." (PMID 30161129, 2018). "MYLKP1 is a cancer-promoting pseudogene whose genetic variants differentially enhance cancer risk in African American populations." (PMID 30161129, 2018). "Mechanistically, MYLKP1 suppresses smMLCK expression by reducing RNA stability, promoting cancer cell proliferation, highlighting its role in tumorigenesis." (PMID 40556338, 2025). "For instance, pseudogenes DUXAP8, MST O 2P and MYLKP1 involved in supporting CRC progression and enhance cancer risk." (PMID 36866106, 2022). "The wild type vector, utilizing the major allelic pairing (rs12490683-G and rs12497343-C) showed MYLKP1 to be significantly upregulated in cancer cells (H522) over epithelial cells (Beas-2b) (p<0.05)." (PMID 30161129, 2018). "We have previously shown MYLKP1 expression in cancer cell lines inhibits the expression of MYLK in cancer cells." (PMID 30161129, 2018). "MYLKP1 promoter luciferase reporter assays were conducted in a human adenocarcinoma cell line (H522) and a non-cancer cell line (Beas2b)." (PMID 30161129, 2018). "Cancer cell lines, H441 and A549, exhibited increased MYLKP1 expression, increased MYLKP1 luciferase promoter activity, increased proliferation and migration." (PMID 30161129, 2018). "We now show that MYLKP1 selectively transcribes mRNA in cancer cells and dramatically decreases the expression of the functional MYLK." (PMID 30161129, 2018). "The potential for cross-talk between the parent gene and the pseudogene (MYLK and MYLKP1) and nmMLCK's potential as a cancer biomarker provide unique targets for cancer therapeutics that have the potential to affect cancer cell proliferation." (PMID 30161129, 2018). "Mechanistically, MYLKP1 overexpression inhibits smMLCK expression in cancer cells by decreasing RNA stability, leading to increased cell proliferation." (PMID 22613733, 2012). "Moreover, expression of the pseudogene increases cell proliferation of normal and cancer cells, indicating an active role of MYLKP1 during carcinogenesis." (PMID 30161129, 2018). "Two promoter SNPs (rs12497343 and rs12490683) in the MYLKP1 promoter region are promising candidates that could contribute to the regulation of MYLKP1 in cancer." (PMID 30161129, 2018). "Thus, mechanistically, MYLKP1 over-expression dramatically inhibits smMLCK expression in cancer cells and increases cell proliferation." (PMID 30161129, 2018). "Moreover, MYLKP1 and smMLCK exhibit negatively correlated transcriptional patterns in normal and cancer cells with MYLKP1 strongly expressed in cancer cells and smMLCK highly expressed in non-neoplastic cells." (PMID 22613733, 2012). "Furthermore, transfection of a MYLKP1 promoter luciferase reporter harboring the minor allelic pairing (rs12497343-G and rs12490683-A) into H522 cancer cells resulted in significantly greater promoter activity (p<0.05) when compared to the major allelic pairing in H522 cancer cells." (PMID 30161129, 2018). "We previously demonstrated that MYLKP1 is selectively expressed in cancer cells, functions as a regulator of MLCK levels, and increases cancer cell proliferation in vitro." (PMID 30161129, 2018). "We identified MYLKP1 as a pseudogene of MYLK that regulates levels of cellular MLCK and is selectively expressed in cancer cells, a finding observed with other pseudogenes." (PMID 30161129, 2018).
cancer (continued). "We employed this method to detect MYLKP1 expression in several cell lines including human cancer cells (H23, H460, H441) and non-cancer epithelial cells (Beas2b) transfected with the MYLKP1 plasmid." (PMID 30161129, 2018). "Previously, we have shown that an upregulation in MYLKP1 mRNA expression produces a functional transcript in multiple cancer cell lines, and this corresponds with the downregulation of functional MYLK mRNA in cancer cell lines." (PMID 30161129, 2018).
MYLKP1 also shares sentences with these, for which no sentence is quoted: adenocarcinoma (1 paper); bladder carcinoma (1); gastric cancer (1); leukemia (1); liver cancer (1); tumor (1).